NCOA4 (nuclear receptor coactivator 4)
Diseases named in the same sentence as NCOA4 in open-access papers (continued):
Sharing a sentence is not in itself a finding about the gene and the disease.
secondary progressive MS (1 paper, 2024). "Autopsy samples from individuals with secondary progressive MS (SPMS) showed NCOA4 expression in macrophages and oligodendrocytes at the mixed active/non-active lesion edge, with iron ferritin-positive cells and iron-containing cells present in this region." (PMID 38965216, 2024).
synovitis (1 paper, 2022). Inflammation of a synovial membrane. "A paper in 2021 showed that the iron content and the expression of TfR1 and NCOA4 in synovitis cells increased, while the expression of GPX4, SLC7A11, SLC3A2L, and NRF2 decreased in LPS-induced synovitis cell model, resulting in increased synovitis cells death and decreased cell viability." (PMID 35958605, 2022).
Telangiectasia (1 paper, 2025). Telangiectasias refer to small dilated blood vessels located near the surface of the skin or mucous membranes, measuring between 0.5 and 1 millimeter in diameter. "Additionally, the Ser/Thr protein kinase ATM (ataxia telangiectasia mutated) regulates intracellular labile-free iron by phosphorylating NCOA4, which facilitates the interaction between NCOA4 and ferritin, thus maintaining ferritinophagy." (PMID 39856053, 2025).
testicular tumor (1 paper, 2024). "In the DSEMs and LCTs, NCOA4 expression was considerably higher than in other canine testicular tumor types, while the expression of FTH1 appeared lower." (PMID 39272404, 2024). "In the testicular tumors, the expressions of TfR1, FTH1 and NCOA4 were altered compared to the non-neoplastic samples." (PMID 39272404, 2024).
thyroid nodule (1 paper, 2025). A small circumscribed mass in the THYROID GLAND that can be of neoplastic growth or non-neoplastic abnormality. "Therefore, the targets widely recognized and recommended by scholars at home and abroad were selected to compose a 6-gene test panel for thyroid nodule diagnosis, including BRAF V600E mutation, TERT mutation, and gene fusions (CCDC6-RET, NCOA4-RET, ETV6-NTRK3, EML4-NTRK3, STRN-ALK, and PAX8/PPARG)." (PMID 40586006, 2025).
uterine cancer (1 paper, 2022). Primary or metastatic malignant neoplasm involving the uterine corpus and/or the cervix. "According to our findings, the modification frequency (>5%) with “mutation” of NCOA4 is higher in primary uterine cancers." (PMID 35756082, 2022).
tumor (99 papers, 1998 to 2026). "Abnormal NCOA4 expression is observed in various tumor cells, and its abnormal expression can contribute to the malignancy of some tumor cells and is significantly associated with cancer prognosis." (PMID 40788949, 2025). "Tumor-associated M2 macrophages exhibited FTH1 upregulation with concurrent NCOA4 suppression, suggesting adaptive iron sequestration as a ferroptosis resistance mechanism." (PMID 40765825, 2025). "Studies have reported that high expression of NCOA4 is associated with prolonged overall tumor survival." (PMID 37072786, 2023). "We also analyzed NCOA4 DNA methylation in normal and primary tumor tissues and investigated possible functional pathways underlying NCOA4-mediated oncogenesis." (PMID 35756082, 2022). "Then, we utilized the GEPIA2 program to integrate all of the TCGA's tumor expression data and identified the top 100 genes that were significantly linked with NCOA4 expression." (PMID 35756082, 2022). "In cancer cells, NCOA4 is a critical regulator of ferroptosis, and mutations in NCOA4 can lead to decreased ferroptosis of tumor cells by reducing intracellular free iron accumulation, glutathione synthesis, and reactive oxygen species, among other effects (ROS)." (PMID 35756082, 2022). "It is conceivable that increased expression of NCOA4 is associated with tumor initiation, as reflected by its association with risk in solely normal tissue, while decreased expression of MSMB is associated with both tumor initiation and maintenance or progression." (PMID 21085629, 2010). "Notably, associations between rs10993994 genotype and expression of MSMB and NCOA4 are observed in histologically normal prostate tissue, whereas in tumor tissue an association is detected with only MSMB (albeit at an attenuated level relative to the normal tissue)." (PMID 21085629, 2010). "In lung adenocarcinoma, the silencing of NCOA4 gene expression significantly promotes tumor cell proliferation, invasion, and metastasis." (PMID 40788949, 2025). "Conversely, NCOA4 has the potential to induce ferroptosis in tumor cells by facilitating the degradation of FTH and promoting ferritinophagy within autophagosomes." (PMID 40420092, 2025). "While, NCOA4 exerted its function of inhibiting tumor development by affecting FTL to regulate the ESCC sensitivity to ferroptosis." (PMID 41281761, 2025). "NCOA4 has also been shown to play a role in cellular ferroptosis and to exert tumour-suppressive effects in cancers." (PMID 40794264, 2025). "Evidence from mouse models indicates that NCOA4 knockout significantly delays tumor progression and prolongs survival, whereas its overexpression accelerates tumor growth." (PMID 41200204, 2025). "NCOA4 is a specific receptor that mediates the occurrence of autophagy in ferritin and plays an important role in tumor development." (PMID 40788949, 2025). "Studies have shown that high expression of NCOA4 in PDAC leads to increased NCOA4-mediated ferritinophagy, a process that supports tumor cell proliferation by maintaining iron homeostasis." (PMID 41200204, 2025). "NCOA4 is closely related to the development of many cancers, plays a regulatory role in their biological behavior, and is involved in tumor growth and metastatic spread." (PMID 40788949, 2025). "It was found that NCOA4 is involved in anti-infection and anti-tumor immunity via an influence of the level of iron or interaction with specific proteins." (PMID 38961066, 2024). "BECN1, ELAVL1, and ATG16L1 were highly expressed in tumor tissues, while NCOA4, FTH1, FTL, SNCA, TNF, ATG7, and ZFP36 showed low expression levels." (PMID 39593730, 2024). "Previous studies have shown that intestinal hepato-like tumours are more common in the context of IBD and that hepato-like tumours have recurrent changes in molecular characteristics, including NCOA4-RET fusion." (PMID 37291580, 2023).
tumor (continued). "In vivo, we discovered that caryophyllene oxide can lower tumor volume, significantly improve NCOA4 and LC3 protein levels in tumor tissue, and raise Fe2+ and malondialdehyde levels in serum." (PMID 35899120, 2022). "NCOA4 has the potential to play a critical role in cancer development and progression, as it is thought to be involved in tumor growth and metastasis spread." (PMID 35756082, 2022). "Using the GO|KEGG pathway analysis, we discovered that “DNA damage checkpoint,” “negative regulation of translation,” and “mRNA catabolic process” were the top hits, indicating that these pathways are engaged in NCOA4's role in tumor pathogenesis regulation." (PMID 35756082, 2022). "The GO|KEGG pathway analysis indicated “DNA damage checkpoint,” “negative regulation of translation,” and “mRNA catabolic process” as top hits, suggesting that these pathways are involved in NCOA4's tumor pathogenesis-regulating function." (PMID 35756082, 2022). "On the other hand, moderate and strong staining patterns for CD44, DPP4, and SLC7A11 were observed in the cytoplasm and cell membrane of tumor tissues, while NCOA4 only exhibited weak positive staining on the cell membrane of tumor tissues." (PMID 34370716, 2021). "In NIH3T3 NCOA4-RET tumours, 0.3, 1 and 3 mg/kg doses were all able to inhibit RET up to 12 h, with RET phosphorylation being partially restored after 24 h." (PMID 34373541, 2021). "The gene expression level of NCOA4 was significantly lower in tumor samples in comparison to normal tissues of ccRCC in TCGA database(p = 7.337e-2), which was also validated in GEO database (p = 4.696e-05, 0.018)." (PMID 33402128, 2021). "A recent study revealed that NCOA4 expression decreased in ccRCC tumor tissue compared to normal tissue." (PMID 34922551, 2021). "Two of the detected gene fusions have been previously reported in PTCs, SQSTM1-NTRK3 (case 2, both primary tumor and metastasis) and NCOA4-RET (case 5, both primary tumor and metastasis)." (PMID 33827048, 2021). "NCOA4 can also affect the recognition of tumor cells by interfering with interferon-γ (IFN-γ) receptor signaling." (PMID 34178024, 2021). "But lower NCOA4 expression level was observed in higher T stage and M stage and tumor stage (p = 1.917e-05, 7.948e-04, 7.978e-06), as well as in higher grade and ccRCC classification (p = 2.428e-04, 2.9283e-08)." (PMID 33402128, 2021). "In patient-derived tumor cells (PDCs) with nuclear receptor coactivator 4 (NCOA4)-RET fusion obtained from the brain metastasis of a 63-year-old mCRC patient, vandetanib revealed a significant antitumor effect in terms of cell viability to CRC-PDCs." (PMID 32413973, 2020). "Cabozantinib was added as a genomic-guided targeted therapy based on the NCOA4-RET fusion observed in the recurrent tumor." (PMID 30446652, 2018). "Ponatinib displayed 79% tumor growth inhibition in the NCOA4-RET model (CR1520) and near complete regression in the CCDC6-RET model (CR2518)." (PMID 30038711, 2018). "Immunohistochemistry revealed positive staining for the proliferation marker Ki-67 for RETamp, ΔRET, and NCOA4-RET tumor tissues." (PMID 30446652, 2018). "In order to offset the time for tumor formation, 0.5×106 cells were injected for NCOA4-RET, whereas 5×106 cells were injected for ΔRET and RETamp in athymic nude mice." (PMID 30446652, 2018). "Tumor protein, collected at the end of treatment on day 14 for NCOA4-RET and ΔRET, revealed significant reduction in the fusion protein levels and downstream PI3K-AKT signaling for the cabozantinib-treated groups as measured by western blot." (PMID 30446652, 2018). "In conclusion, we demonstrated that alectinib has inhibitory effects on tumor cells with NCOA4-RET in vitro and in vivo." (PMID 29088743, 2017). "In the present study, we investigated the effect of alectinib on NCOA4-RET utilizing native tumor cells with this type of RET fusion." (PMID 29088743, 2017).
tumor (continued). "In the present study, we investigated the effects of alectinib on NCOA4-RET fusion-positive tumor cells in vitro and in vivo." (PMID 29088743, 2017). "In the present study, we demonstrated that alectinib is effective at inhibiting native tumor cell lines harboring NCOA4-RET (EHMES-10)." (PMID 29088743, 2017). "Expression levels of MSMB and NCOA4 transcripts were significantly higher in normal compared with tumor tissue (p<0.0001), consistent with previously published reports." (PMID 21085629, 2010). "The observed alterations in iron regulation, including increased FTH1 and decreased NCOA4, point to a shift in iron storage capacity that may contribute to immunosuppression in the tumor microenvironment." (PMID 40765825, 2025). "Inducing ferroptosis of tumor cells via enhancement of NCOA4-mediated ferritinophagy may constitute a potential therapy for cancers." (PMID 38961066, 2024). "Different NCOA4 isoforms exert disparate effects on tumor progression." (PMID 38961066, 2024). "However, as SCTs are characterized by low proliferation rates, confirmed by PCNA expression only in a few neoplastic SCs, our results showed that NCOA4-driven ferritinophagy is enough to support proliferation in this type of tumor." (PMID 39272404, 2024). "Among the fourteen ferritinophagy-related genes studied, ten exhibited significant differences between tumor and normal samples: NCOA4, FTH1, FTL, SNCA (all p < 0.0001), BECN1 (p = 0.031), ELAVL1 (p = 0.00023), TNF (p = 0.00074), ATG16L1, ATG7, and ZFP36 (all p < 0.0001)." (PMID 39593730, 2024). "In contrast, large tumor size, more aggressive types like the tall-cell type, angioinvasion, perineural invasion or extrathyroidal extension were independent predictive factors of NCOA4::RET." (PMID 37188126, 2023). "Similarly, compared to that in peritumor tissues, the expression of ferroptosis-inducing genes, including PTGS2, HMOX1, TFR2, and NCOA4, was down-regulated in tumor tissues, whereas ferroptosis-suppressor genes SLC7A11 and FTH1 were upregulated." (PMID 37554285, 2023). "Thus, we used the TIMER, CIBERSORT, CIBERSORT-ABS, TIDE, XCELL, MCPcounter, QUANTISEQ, and EPIC algorithms to investigate the relationship between immune cells infiltration and NCOA4 expression in several TCGA tumor types." (PMID 35756082, 2022). "Indeed, patient-derived CRC tumor cells harboring NCOA4-RET fusion were sensitive to the treatment with vandetanib, a multi-kinase inhibitor with non-selective RET activity." (PMID 35957881, 2022). "Notably, the expression of NCOA4 protein was much greater in peritumoral neighboring tissues than in tumor tissues (Figures 7aand 7b)." (PMID 35756082, 2022). "Additionally, we included factors such as survival status, genetic alterations such as DNA methylation, and critical cellular downstream pathways in our analysis of NCOA4 expression levels among tumor types." (PMID 35756082, 2022). "Most scholars consider that NCOA4 might play a critical role in cancer progression; for instance, it is thought to be involved in tumor growth and metastasis." (PMID 36552889, 2022). "In addition, the expression level of NCOA4 in ccRCC samples is lower than that in paired non-tumor samples (p < 0.05)." (PMID 34370716, 2021). "Contrast to normal tissue, NCOA4 expression was lower in ccRCC tumor tissue(p < 0.05)." (PMID 33402128, 2021). "At the end of tumour growth experiment, phosphorylation of NCOA4-RET G810R and TPM3-TRKA G595R confirmed their strong resistance to Pz-1, with only NCOA4-RET G810R showing some rate of inhibition at the highest used dose (3 mg/Kg), possibly explaining the partial tumour growth inhibition." (PMID 34373541, 2021). "Mechanistically, a large number of biomolecules and tumor-associated signaling pathways, including DECR1, PANX2, HSPB1, ACOT8, SUV39H1, NCOA4, PI3K-AKT-mTOR signaling, VHL/HIF-2α pathway, and Hippo/TAZ signaling pathway, have been reported to regulate ferroptosis in urologic cancers." (PMID 34922551, 2021).
tumor (continued). "Whether NCOA4 functions differently depending on the cancer context and understanding whether the ferritinophagy specific function of NCOA4 drives tumor effects are critical questions for future study." (PMID 30360520, 2018). "Each isoform of MSMB and NCOA4 was expressed in both normal and tumor prostatic tissue." (PMID 21085629, 2010). "Expression levels of TIMM23, the next closest gene to the risk locus and 1.4 kb telomeric to NCOA4, are not correlated with genotype status in either normal or tumor tissue." (PMID 21085629, 2010). "Thus, the relationship between NCOA4 isoforms and tumor progression requires further elucidation." (PMID 38961066, 2024). "NCOA4 expression levels, however, are no longer associated with genotype in tumor tissue (p>0.30)." (PMID 21085629, 2010). "Concurrently, intracellular tryptophan levels were found to inhibit NCOA4‐mediated selective autophagy of FTH1, stabilising FTH1 levels and promoting tumour survival." (PMID 40504108, 2026). "Genetic or pharmacological inhibition of AURKA restored NCOA4-mediated ferritinophagy, synergized with ferroptosis inducers (sorafenib or IKE), and potently suppressed tumor growth both in vitro and in vivo." (PMID 42026022, 2026). "NCOA4 and FTH1 are involved in iron metabolism and ferroptosis, with NCOA4 acting as a tumor suppressor and FTH1 promoting tumor progression." (PMID 40649942, 2025). "Studies show that downregulating EZH2 activates Nuclear Receptor Coactivator 4 (NCOA4) to trigger ferroptosis in cancer and enhances antitumor immunity by promoting CD8 + T cell infiltration into tumor tissues." (PMID 41326356, 2025). "Here, we identify nuclear receptor coactivator 4 (NCOA4), a ferritinophagy receptor, as a context-dependent tumor suppressor that coordinates cytosolic and mitochondrial iron handling in CRC." (PMID 41041538, 2025). "Thus, NCOA4 may be involved as an important molecule in anti-tumor and anti-infection immunity." (PMID 38961066, 2024). "Caryophyllene oxide treatment reduced tumor volume enhanced NCOA4 and LC3 protein levels in tumor tissues, and increased Fe2+ and malondialdehyde levels in the blood." (PMID 38738178, 2024). "The expression of all six FRGs was significantly different (p < 0.05), with FTH1, FTL, and PCBP1 being overexpressed in the tumor group and ZFP36, NCOA4, and TNF expressed less in the tumor group." (PMID 37555866, 2023). "Genomic profiling salivary duct carcinomas (SDCs) reveals that RET is frequently altered in this tumor type, with three clinical cases presenting with RET fusion products, CCDC6-RET or NCOA4-RET." (PMID 35957881, 2022). "We also investigated the expression of GPX4, 4-HNE, GOT1, NCOA4, FTH, and LC3B in tumor tissues using IHC staining." (PMID 36387145, 2022). "The proportion of macrophages was definite for AR (R = 0.379, P < .001), after adjusting for tumor purity, and similar results were illustrated for NCOA2 (R = 0.392, P < .001) and NCOA4 (R = 0.165, P < .001)." (PMID 31355524, 2019). "Treatment with 60 and 30 mg kg−1 effectively inhibited tumor growth for NCOA4-RET xenografts and resulted in rapid regression of the tumor within 2 weeks." (PMID 30446652, 2018). "Based on experiments described in NIH/3T3 cells, NCOA4-RET was observed to be the fastest growing cell line and this translated to tumor formation in less than 2 weeks; whereas ΔRET and RETamp were slower in comparison, taking longer than a month." (PMID 30446652, 2018). "NCOA4 overexpression reverses these effects, reducing MCU expression and tumor growth." (PMID 41041538, 2025). "In our study, tumor tissues from 83 PTC patients were investigated to determine the prevalence of CCDC6::RET and NCOA4::RET rearrangements in Thailand and to explore the association between the mRNA expression of CCDC6::RET and NCOA4::RET rearrangements and clinicopathology." (PMID 37188126, 2023).
tumor (continued). "To determine whether ferritinophagy is required for 4OI-mediated tumor suppression, we assayed the level of FTH1 in control and NCOA4-knockdown Y79-CR cells." (PMID 35654783, 2022). "Because of this, integrating NCOA4 and TME research may provide novel insights into tumor treatment." (PMID 35756082, 2022). "We further investigated the expression of NCOA4 in the GTEx database for some tumor types for which normal tissue data were not available in TCGA." (PMID 35756082, 2022). "Importantly, NCOA4-RET G810R tumour growth remained virtually unaffected by 0.3 and 1 mg/Kg doses; only 3 mg/Kg treatment was able to reduce tumour volume by about 50%." (PMID 34373541, 2021). "Treatment with 0.3 mg/Kg of Pz-1 was able to completely block NIH3T3 NCOA4-RET but not TPM3-TRKA tumour growth." (PMID 34373541, 2021). "Therefore, we analyzed the correlation of NCOA4 expression with six kinds of infiltrating immune cells (CD8+ T cells, CD4+ T cells, B cells, dendritic cells macrophages, and neutrophils) and tumor purity." (PMID 33402128, 2021). "While the cell of origin responsible for increased NcoA4 serum transcripts is not known, a possibility is that they are derived from tumor cells undergoing cell death/apoptosis." (PMID 22562579, 2012). "Currently, NCOA4 function differently depends on the cancer context, while robust evidence for the role of ferritinophagy in tumorigenesis is lacking; here, we presented that NCOA4-mediated ferritinophagy contributed to EMT inhibition, which may enrich our knowledge for NCOA4 in tumor development." (PMID 31320987, 2019).